GRN (granulin precursor)
Diseases named in the same sentence as GRN in open-access papers (continued):
Sharing a sentence is not in itself a finding about the gene and the disease.
breast cancer (36 papers, 2006 to 2026). A primary or metastatic malignant neoplasm involving the breast. "As GRN was shown to be an important therapeutic and diagnostic target in breast cancer, GRN diagnostic kits and neutralizing antibodies are being developed." (PMID 34366786, 2021). "GRN is associated with poor prognosis in BC, and specifically in triple-negative breast cancer, a population of bone marrow cells secretes GRN to support stromal activation and robust tumor growth in young mice." (PMID 32626702, 2020). "GRN is a secreted cytokine found to affect CSCs in breast cancer, besides being involved in therapy resistance in a range of cancer types." (PMID 38546390, 2024). "In another study, exosomes derived from GRN−/− TAM inhibited breast cancer cell migration and invasion." (PMID 36980592, 2023). "GRN was also secreted from the bone marrow cells and supported the stromal activation and tumor growth in mouse breast cancer models." (PMID 28211531, 2017). "This is reminiscent of progranulin action in breast cancer, where progranulin (PCDGF/granulin precursor) expression is stimulated by estradiol and progranulin regulates estrogen-dependent mitogenesis." (PMID 27512385, 2016). "The growth factor GRN stimulates progression and metastasis of breast cancer and is involved in a variety of cancers such as clear cell renal carcinoma, invasive ovarian carcinoma and glioblastoma." (PMID 16893473, 2006). "In addition, previous studies have reported that TAMs were related to tumor vascularization, and expression of GRN by TAMs was able to increase their angiogenic potential in breast cancer." (PMID 35523772, 2022). "High GRN expression has been detected in many types of cancer and elevated serum GRN levels could be used as a potential prognostic biomarker in for example breast cancer, chronic lymphocytic leukemia, and non-small-cell lung carcinoma." (PMID 34366786, 2021). "Notably, using the same breast cancer TMA as in this study, GRN expression was found to correlate with the same clinicopathological features as CD163+ macrophages in TS as well as with the density of CD163+ macrophages in TS." (PMID 22824040, 2012).
Parkinsonism (32 papers, 2010 to 2025). Characteristic neurologic anomaly resulting from degeneration of dopamine-generating cells in the substantia nigra, a region of the midbrain, characterized clinically by shaking, rigidity, slowness of movement and difficulty with walking and gait. "Up to 41% of FTD patients with GRN mutations exhibit parkinsonism." (PMID 29692703, 2018). "Parkinsonism precedes the cognitive and behavioral symptoms of FTD by several years in patients with mutations in GRN." (PMID 29692703, 2018). "In previous reports, parkinsonism and Richardson syndrome have been described in association with MAPT pathogenic variants,25, -, 27 but in our overall cohort, motor signs of a PSP-MP, PD-MP, and CBS-MP occurred most frequently in c9orf72 followed by GRN pathogenic variant carriers." (PMID 35948443, 2022). "In addition, parkinsonism occurs in some FTD patients and is more common in those patients (up to 41%) with GRN haploinsufficiency." (PMID 29692703, 2018).
Atrophy (29 papers, 2010 to 2025). Any weakening or degeneration, especially through lack of use. "Neuroimaging studies have shown that individuals with the C9orf72 mutation exhibit symmetry patterns of atrophy in frontal, temporal, and parietal lobes, in contrast to asymmetric atrophy observed in GRN-mutated individuals." (PMID 41516057, 2025). "Two PPA-NOS patients had a GRN mutation, which is known to demonstrate particularly high rates of atrophy, and it is important to highlight that these initial results are based on a small cohort (n = 6)." (PMID 34626889, 2021). "GRN pathogenic variant carriers generally had minimal increases in atrophy rates between the presymptomatic and mild stages, with rapid increases in atrophy rates in the symptomatic stages." (PMID 33112398, 2020). "The strongest association between GRN expression and the atrophy pattern in symptomatic GRN mutation carriers was measured with microarray probe CUST_13046_PI416261804, which showed a non-significant positive association z = 1.31 (PFDR=0.13)." (PMID 33210084, 2020). "In GRN mutation carriers, asymmetric atrophy is a common finding with left or right asymmetry reported even within the same family." (PMID 32184751, 2020). "Around the time of symptom onset, there seems to be a more gradual progression of atrophy in MAPT mutation carriers but a rapid change in volume loss in GRN carriers." (PMID 31119452, 2019). "VBM revealed multiple frontal-predominant clusters (in white matter more than gray matter) where elevated markers of inflammation were associated with more severe atrophy in GRN mutation carriers." (PMID 31620075, 2019). "C9orf72 repeat expansion carriers had a greater degree of atrophy, as compared to GRN mutation carriers and MAPT mutation carriers, with the latter being the smallest group in our sample." (PMID 28460069, 2017). "Brain imaging showed a symmetrical pattern of atrophy, which would be in keeping with an expansion in C9orf72, whereas GRN mutations show a more asymmetrical pattern of atrophy." (PMID 24286341, 2014). "The GRN mutation group showed asymmetrical atrophy whereas the MAPT group showed symmetrical atrophy." (PMID 20045477, 2010). "Despite the lack of imaging data for 13 GRN patients, these observations are concordant with those of previous studies, demonstrating that GRN mutations are associated with widespread and asymmetric atrophy that concerns the frontal, temporal, and parietal lobes." (PMID 33467748, 2021). "Interestingly, multiple neuroimaging studies have shown that GRN mutations are associated with marked asymmetrical cortical atrophy, with either left or right sided predominance." (PMID 32052166, 2020). "There has been less focus on longitudinal investigation of grey matter atrophy; however, rates of atrophy vary between genetic groups with faster rates in GRN mutation carriers during the symptomatic period (allowing measurement over short time periods:) compared with the other groups." (PMID 31119452, 2019). "It is unclear why fewer are seen in these two groups although this may be related to underlying atrophy of the basal ganglia which tends to be seen in the GRN and MAPT groups to a greater extent than in the C9orf72 group." (PMID 28529873, 2017). "Recent studies have shown that mutations in GRN are correlated with atrophy of the parietal lobes." (PMID 26973510, 2016). "These inconsistencies might be due to the age at examination, the proximity to onset of clinical symptoms, associated lobar cortical atrophy changes, the sample size of GRN mutation carriers, and the statistical analysis methodology with different sensitivity and specificity." (PMID 32184751, 2020). "Larger sample sizes are needed to further explore the neuroimaging correlates of SNQ‐NL performance, given subcortical atrophy (most specifically of the thalamus) is a consistent finding in genetic subtypes of FTD44, 45 and is found to be associated with facial ER in GRN mutation carriers." (PMID 39229325, 2024).
Atrophy (continued). "In the bvFTD case due to GRN mutation, voxel-wise analysis showed loci with W-scores ≥ 1.654, but the spatial pattern did not match that of atrophy in this individual, nor atrophy in GRN FTD cases generally." (PMID 36513817, 2023). "Finally, a pattern of asymmetric cortical atrophy with parietal involvement was found in two subjects with FTD and premorbid affective disorder; both subjects shared GRN mutations, notably the g.11019 11022delCACT." (PMID 34925096, 2021). "There were no other significant differences between GRN mutation carriers with different atrophy patterns." (PMID 32052166, 2020). "In a longitudinal study of asymptomatic GRN mutation carriers with a 20-month follow-up, no gray matter volume loss was found at baseline, but left inferior and middle temporal gyri atrophy was reported 20 months later." (PMID 32184751, 2020). "In order to investigate this further, the longitudinal change in load, location and appearance of WMH, and their relationship to other neuroimaging measures of atrophy or neuropsychological measures of disease severity and progression, in GRN carriers will be an important subject for future study." (PMID 28529873, 2017). "Even genetic variants implicated in FTD show a similar pattern, where patients with MAPT mutations have greater left‐sided frontal atrophy, while those with the GRN mutation had greater right‐sided atrophy, and C9ORF72 carriers tended to show a symmetric pattern of atrophy." (PMID 28031997, 2016). "Structural neuroimaging in patients with C9orf72 expansions does not reveal a characteristic pattern of atrophy, unlike GRN or MAPT mutations." (PMID 26388768, 2015). "Using simply applied visual rating scales, we have identified typical patterns of atrophy for each group of mutation carriers: anterior and medial temporal for MAPT, asymmetric frontal (orbitofrontal, cingulate, frontoinsular) and parietal for GRN and widespread for C9ORF72." (PMID 29793546, 2018). "Even in regions where the rate of volume loss increased between the mild and symptomatic stages in C9orf72+ carriers, the magnitude of acceleration of atrophy between these 2 stages was much higher in MAPT+ and GRN+ carriers." (PMID 33112398, 2020). "We used visual rating scales to investigate whether identifying atrophy in these areas may be helpful in distinguishing symptomatic patients carrying different causal mutations in the microtubule-associated protein tau (MAPT), progranulin (GRN) and chromosome 9 open reading frame (C9ORF72) genes." (PMID 29793546, 2018). "Using an average of the best performing direct measure, the current study reports a similar pattern of results, with annual atrophy rates of 1.8 (0.9)% in MAPT, 1.6 (1.1)% for C9orf72 and 3.1 (2.0)% for GRN patients, who conclusively exhibit the highest rate of change across subgroups." (PMID 34626889, 2021). "In most patients, right and left sides were strongly correlated, without lateralized atrophy, as occurs in FTD patients with mutations in the GRN gene." (PMID 27995069, 2016). "The individual with bvFTD due to GRN mutation showed largely similar results on the SUVR map as sporadic and C9orf72 bvFTD but had loci of elevated binding in the superior cerebellum and the temporal lobe that overlapped but did not correspond to observed atrophy." (PMID 36513817, 2023).
Obesity (28 papers, 2012 to 2025). Accumulation of substantial excess body fat. "On the contrary, GRN can exhibit a pro-inflammatory effect by promoting the expression of proinflammatory cytokines such as IL-6 and IL-8 in different diseases such as psoriasis, obesity, and systemic lupus erythematosus." (PMID 38854033, 2024). "It is also important to note that the novel EC proteins, APP, CAD, BRD2 (which is part of DKFZp313H139), CST3, GRN, PPM1G and ZC3H4, have all been reported to be positively associated with obesity or adiposity, whilst the novel EC protein SLC25A24 may even prevent obesity and promote leanness." (PMID 37760635, 2023).
proteinopathy (25 papers, 2014 to 2025). "This is in accordance with the underlying proteinopathy, as GRN and C9ORF72 genetic patients are associated with a TDP-43 deposition, whereas MAPT genetic patients are characterized by a tau protein deposition." (PMID 36499048, 2022). "Patients harboring loss of function granulin (GRN) mutations display TDP‐43 proteinopathy." (PMID 39318236, 2025). "This suggests that GRN mutations causing PGRN reduction may be causative or represent risk factors for multiple proteinopathies (TDP-43 proteinopathy, tauopathy or α-synucleinopathy)." (PMID 28473694, 2017). "Three groups reported significant macular changes in proteinopathies compared to healthy controls, including reduced macular volume in subjects with progranulin (GRN) mutations (which are associated with TDP-43 neuropathology), and thinning in six macular sectors in subjects with PSP." (PMID 36278002, 2022). "Importantly, it is still not clear whether sporadic and familial cases, or even the different mutations with converging proteopathies (e.g., GRN or C9orf72), share the same pathophysiological processes, which can ultimately impact the body-fluid biochemical profiles." (PMID 34680117, 2021). "In four patients carrying the IVS1 + 5G > C GRN mutation, we also found a mild TDP proteinopathy in the occipital cortex." (PMID 29370838, 2018). "Therefore, this study focused on complement activation in microglia from GRN variants to define the linkage between the complement system and TDP-43 proteinopathy." (PMID 38347588, 2024). "This variation could be explained by the inclusion of different FTD biochemical profiles, which likely differ between sporadic and familial cases with the same proteopathy, or even between genetic backgrounds of the same pathological subtypes (e.g., GRN and C9orf72)." (PMID 40866991, 2025). "Different studies have elicited the co-occurrence of proteinopathies in patients carrying a GRN mutation, whereas other groups could not confirm this." (PMID 29370838, 2018). "In addition to sporadic forms, several mutations in different genes, including the C9orf72 (most frequent), granulin (GRN), valosin-containing protein (VCP), TARDBP, SQSTM1 (sequestome), DCTN1 (dynactin), and OPTN (optineurin) have been reported to be associated with TDP-43 proteinopathy." (PMID 26848654, 2016). "Clearly defining the functional alterations sustaining GRN pathology is crucial both for a better understanding of the disease, and in order to define biomarkers to test disease-modifying drugs against TDP43 proteinopathies." (PMID 25188321, 2014).
rheumatoid arthritis (24 papers, 2013 to 2026). A chronic, systemic autoimmune disorder characterized by inflammation in the synovial membranes and articular surfaces. "Furthermore, recent studies have shown that GRN is correlated with autoimmune diseases, including rheumatoid arthritis, multiple sclerosis and type-2 diabetes." (PMID 23755248, 2013). "Furthermore, the elevation of GRN levels was observed in local inflammatory tissues of patients with autoimmune diseases, such as brains in patients with active multiple sclerosis, and synovium of rheumatoid arthritis patients." (PMID 23755248, 2013). "GRN competitively binds with TNFR1/2 to disrupt TNF-α function, which in turn leads to increased IL-10 production in T regulatory cells in conditions such as rheumatoid arthritis and inflammatory bowel disease." (PMID 39143467, 2024).
primary progressive aphasia (21 papers, 2010 to 2025). Primary progressive aphasia (PPA) is a neurodegenerative disorder, characterized by a primary dissolution of language, with relative sparing of other mental faculties for at least the first 2 years of illness. "A partial deletion in the ABCA7 gene and a variant in the GRN gene has been found in a patient with semantic variant of primary progressive aphasia, one of the clinical phenotypes associated with FTLD-TDP." (PMID 36385764, 2022). "While behavioral variant FTD (bvFTD) was the most frequently identified phenotype, several patients with GRN mutations were also diagnosed with primary progressive aphasia (PPA), corticobasal degeneration syndrome (CBDS), Lewy body dementia (LBD), or AD-like symptoms." (PMID 41155255, 2025). "GRN mutations have been linked to FTD phenotypes, particularly those of the primary progressive aphasia (PPA) subtype." (PMID 36294886, 2022). "The most frequent clinical phenotypes of GRN mutation carriers were behavioral variant frontotemporal dementia (bvFTD), CBS, and primary progressive aphasia (PPA)." (PMID 32184751, 2020). "In contrast, patients carrying GRN mutations are more frequently associated with a phenotype of behavioral FTD (bvFTD) or primary progressive aphasia (PPA), while ALS is not typically considered part of the phenotypic spectrum associated with GRN mutations." (PMID 41399249, 2025). "Furthermore, the GRN gene is linked with GRN-related FTLD with TDP-43 inclusion bodies, neuronal ceroid lipofuscinosis type 11, and primary progressive aphasia and is reported to exhibit autosomal recessive or dominant inheritance." (PMID 38291418, 2024). "Type A is associated with behavioral variant FTD (bvFTD) or nonfluent/agrammatic primary progressive aphasia (naPPA) and mutations in the Progranulin gene (GRN)." (PMID 30875755, 2019). "However, unlike MAPT mutations patients in this group frequently present with primary progressive aphasia (PPA) and GRN mutations are more likely to cause early parietal lobe impairment." (PMID 20045477, 2010).
autoimmune disease (19 papers, 2012 to 2025). A disorder resulting from loss of function or tissue destruction of an organ or multiple organs, arising from humoral or cellular immune responses of the individual to their own tissue constituents. "Progranulin (PGRN) glycoprotein is encoded by 12 out of the 13 exons of the GRN gene on the chromosome 17q21, and it is an anti-inflammatory molecule with effects on various inflammatory, autoimmune diseases, and cancer." (PMID 39519389, 2024). "Granulin (GRN), a multifunctional protein linked to inflammatory diseases, has recently been reported to correlate with the disease activity of autoimmune diseases." (PMID 23755248, 2013). "Furthermore, GRN mutations have also been linked to autoimmunity with multiple studies reporting prominent upregulation of serum GRN levels in individuals with various autoimmune diseases." (PMID 34539672, 2021). "In addition to C9orf72, GRN mutations have also been linked to autoimmunity with multiple studies reporting prominent upregulation of serum progranulin levels in patients with various autoimmune diseases." (PMID 34360544, 2021). "To date, the association between autoimmune disease and FTD has been unified by underlying TDP-43 pathology, and extends to GRN carriers." (PMID 34539672, 2021). "Further studies are required to reveal more-precise mechanisms of PGRN and GRN in human autoimmune diseases and in host defense against microbes." (PMID 23140401, 2012). "This suggests that bvFTD individuals with GRN mutations (not assessed in the present study) in combination with autoimmune disease could have enhanced dysregulation of the glycome." (PMID 34539672, 2021).